TRH (thyrotropin releasing hormone)
Diseases named in the same sentence as TRH in open-access papers (continued):
Sharing a sentence is not in itself a finding about the gene and the disease.
pituitary disease (3 papers, 2015 to 2023). "Systematic evaluation of 359 TRH tests in patients with pituitary disease including measurements of thyroxine (T4), TBG-corrected T4 (T4corr), baseline TSH (TSH0) and relative or absolute TSH increase (TSHfold, TSHabsolute)." (PMID 37850100, 2023). "Since we included only the first TRH test performed in each patient, we suspect that recent pituitary disease may be comparable to critical illness as regards the effect on pituitary thyroid function." (PMID 37850100, 2023). "The TRH test could be reserved to patients with pituitary disease, low T4 levels without convincing signs of CH." (PMID 37850100, 2023).
respiratory depression (3 papers, 2020 to 2023). A decrease in ventilation secondary to impaired signals from the central nervous system. "In recent years, one of the therapeutic actions of TRH that has been most tested is its ability to reverse the respiratory depression induced by opioids." (PMID 37446225, 2023). "The respiratory stimulant effects of TRH and its analogs are relevant for identifying them as potential therapeutic agents in breathing disorders other than opioid-induced respiratory depression, such as those presented by patients with obstructive sleep apnea (OSA)." (PMID 37446225, 2023). "Given that respiratory depression is a frequent complication in patients with opioid treatment or abuse, TRH has again been evaluated as a possible therapeutic agent for reversing opioid-induced breathing depression; however, in humans, its effects have not been observed." (PMID 37446225, 2023). "In fact, since NMDA receptor antagonists such as MK-801 block TRH’s breathing stimulation in morphine-induced respiratory depression, NMDA has been proposed as a mediator of TRH’s effects, instead of acting through MOR." (PMID 37446225, 2023). "Other pharmacological classes assessed for their ability to blunt opioid-induced respiratory depression include PKA inhibitors, GIRK inhibitors, and thyrotropin-releasing hormone (TRH) analogs." (PMID 32089833, 2020). "Experimental drugs that have been tested previously for the reversal of opioid-induced respiratory depression include the 5HT4a receptor agonist BIMU-8, thyrotropin-releasing hormone, nicotinic acetylcholine receptor agonists, ampakines, microglia inhibitors, and D1-receptor agonists." (PMID 33424595, 2020).
anaemia (2 papers, 2022 to 2023). "In haemodialysis patients with anaemia, the TSH response to TRH administration was delayed, which most probably was caused by too high sensitivity of pituitary thyrotropes to T3 and T4 inhibition or by transient decrease in blood supply to this gland." (PMID 36364955, 2022). "Upon correction of anaemia, normal TSH secretion in response to TRH was restored." (PMID 36364955, 2022).
cervical cancer (2 papers, 2023 to 2025). A primary or metastatic malignant neoplasm involving the cervix. "The results of the present study is consistent with previous studies that TRH hypermethylation was detected in oral and oropharyngeal cancer and cervical cancer." (PMID 41465216, 2025). "Our group has previously shown that cg01009664 position of TRH gene was substantially methylated in cervical cancer cases when compared to normal cervical cells." (PMID 41465216, 2025). "Compared to normal cervical cells, the cg01009664 location of thyrotropin-releasing hormone (TRH) was significantly methylated in cervical cancer cases." (PMID 37766209, 2023). "In order to increase the test’s applicability for cervical cancer screening, self-collected specimens (cohort 3) were used to evaluate the clinical accuracy of TRH methylation, and the results were compared to those of clinician-collected specimens (cohort 4)." (PMID 37766209, 2023). "The present study used GSE datasets to scan for CpG methylation in cervical samples with varying degrees of lesion severity and discovered that methylation at the TRH cg01009664 site exhibited a greater difference between normal and cervical cancer patients." (PMID 37766209, 2023). "Importantly, TRH hypermethylation has been consistently observed in many HPV-related cancers, including oral and cervical cancer." (PMID 41465216, 2025).
chronic kidney disease (2 papers, 2021 to 2022). Impairment of the renal function secondary to chronic kidney damage persisting for three or more months. "Previous studies have demonstrated that end-stage renal disease might alter TSH levels by dampening pituitary response to TRH, interfering with TSH diurnal rhythm and glycosylation, and reducing TSH clearance rate." (PMID 34726096, 2021).
clear cell renal cell carcinoma (2 papers, 2018 to 2023). "Other investigations reported that TRH was also hypermethylated in clear cell renal cell carcinomas." (PMID 37766209, 2023).
Cushing syndrome (2 papers, 2018 to 2021). Cushing's syndrome (CS) encompasses a group of hormonal disorders caused by prolonged and high exposure levels to glucocorticoids that can be of either endogenous (adrenal cortex production) or exogenous (iatrogenic) origin. "Lastly, IST caused by TRH administration and Cushing’s syndrome after surgical resection could be excluded by medical interview." (PMID 34205543, 2021). "In horses with Cushing’s syndrome (or pituitary pars intermedia dysfunction [PPID]) a thyrotropin-releasing hormone (TRH) stimulation test can be used for diagnosis, as TRH administration results in increased circulating ACTH and cortisol concentrations in affected horses." (PMID 30362899, 2018).
hypertrichosis (2 papers, 2022 to 2024). Excessive hair growth anywhere on the body. "The presence of hypertrichosis was minimal and intermittent, while 9/12 (75%) of basal and 11/12 (91.7%) of post TRH ACTH concentrations were increased after January 2020." (PMID 36288186, 2022). "Horses that demonstrate mild hypertrichosis do not always have basal or TRH-stimulated ACTH concentrations greater than the DCOV." (PMID 36288186, 2022).
leukemia (2 papers, 2019 to 2023). A malignant (clonal) hematologic disorder, involving hematopoietic stem cells and characterized by the presence of primitive or atypical myeloid or lymphoid cells in the bone marrow and the blood. "TRH was found to be downregulated in various cancers, including cervical squamous cell carcinoma, endocervical adenocarcinoma, and ovarian cancer, but abundantly expressed in leukemia." (PMID 37766209, 2023).
Sepsis (2 papers, 2022 to 2023). Sepsis is defined as life-threatening organ dysfunction caused by a dysregulated host response to infection. "In animal sepsis models, NTIS can be overcomed by thyrotropin releasing hormone (TRH) administration, confirming that stimulation of the pituitary may restore the decreased serum thyroid hormone levels in sepsis." (PMID 37745722, 2023).
thyroid hormone resistance (2 papers, 2012 to 2024). "One way in which weight gain could lead to an increase in serum TSH levels and, subsequently, thyroid hormone levels, is through the stimulatory effect of leptin, an adipose tissue-derived hormone, on thyrotropin-releasing hormone (TRH) or by decreasing thyroid hormone resistance." (PMID 22511976, 2012).
acute promyelocytic leukemia (1 paper, 2022). An aggressive form of acute myeloid leukemia (AML), characterized by arrest of leukocyte differentiation at the promyelocyte stage, due to a specific chromosomal translocation t(15;17) in myeloid cells. "We also observed that the TRH-high group had a lower IC50 for ATRA (p = 0.015), which was used in acute promyelocytic leukemia patients." (PMID 36291567, 2022).
adrenal hyperplasia (1 paper, 2012). "Unfortunately, the workup for aberrant receptors, to confirm ACTH-independent macronodular adrenal hyperplasia, is very tedious and some of the suggested stimuli like TRH or GnRH are not commercially available in the USA." (PMID 23097726, 2012).
alcohol abuse (1 paper, 2022). The use of alcoholic beverages to excess, either on individual occasions ("binge drinking") or as a regular practice. "Some studies have demonstrated a blunted or absent response of TSH to TRH in patients with a history of alcohol abuse." (PMID 36231061, 2022).
anal carcinoma (1 paper, 2025). "Initially, the GSE186859 dataset of anal samples retrieved from NCBI was analyzed and it was found that the TRH gene at cg01009664 was hypermethylated in AIN3/anal cancer samples compared to normal cells." (PMID 41465216, 2025). "The present study focused on TRH methylation in the MSM group, particularly MSM-LHIV because it has a higher risk of developing anal cancer than in HIV-negative MSM." (PMID 41465216, 2025).
anxiety disorder (1 paper, 2022). A category of psychiatric disorders which are characterized by anxious feelings or fear often accompanied by physical symptoms associated with anxiety. "Patients with bipolar II depression and anxiety disorder exhibit a lower TSH level and less response to thyrotropin-releasing hormone (TRH), while emotion also influences thyroid hormones." (PMID 36620687, 2022).
asthma (1 paper, 2018). "Since cold stress is a well-recognized factor in inducing or accelerating asthma, it is likely that the TRH-induced OPs in IA-AVPNs contributes to the genesis or exacerbation of asthma." (PMID 30065655, 2018). "Thus, ion channel blockers that can inhibit the TRH-induced the slow excitatory currents and block the triggering of the OP might function as promising candidates to prevent and treat asthma." (PMID 30065655, 2018).
cardiac hypertrophy (1 paper, 2020). "Thus, TRH may have a substantial role in cardiac hypertrophy." (PMID 32457627, 2020).
Cataplexy (1 paper, 2023). A sudden and transient episode of bilateral loss of muscle tone, often triggered by emotions. "CG-3703, a thyroid-releasing hormone (TRH) analog can increase wakefulness, suppressed both REM sleep, slow-wave sleep, and significantly reduce cataplexy in canine NT127,28." (PMID 37898692, 2023).
cervical (1 paper, 2023). "As far as our knowledge extends, no investigation has been conducted to explore the involvement of TRH in cervical carcinogenesis from the perspectives of gene mutation, protein expression, and epigenetics." (PMID 37766209, 2023).
endometriosis (1 paper, 2024). The growth of functional endometrial tissue in anatomic sites outside the uterine body. "In patients with exaggerated PRL response to LHRH/TRH tests before the treatment of endometriosis, danazol treatment was less effective." (PMID 39407928, 2024). "The results were similar to previous studies: the basal prolactin serum levels as well as prolactin response to TRH stimulation were higher in patients with endometriosis compared to the fertile controls." (PMID 39407928, 2024). "Following TRH administration, a significant increase in prolactin serum concentration was observed in patients with endometriosis, suggesting that some patients with endometriosis exhibit a greater capacity for prolactin secretion than normal women." (PMID 39407928, 2024). "One study investigating the effect of 6 months of danazol treatment found the absence of a significant difference in the basal prolactin levels as well as in the response to the TRH and insulin challenge tests between the controls and patients with endometriosis, before and after danazol treatment." (PMID 39407928, 2024). "Moreover, the PRL response to the LHRH/TRH test was exaggerated in patients with endometriosis compared to the normal controls." (PMID 39407928, 2024). "It seems that danazol treatment of endometriosis does not lower the basal prolactin level as well as the response to the TRH and insulin challenge tests." (PMID 39407928, 2024).
epileptic encephalopathies (1 paper, 2023). "TRH use has been reported in West and Lennox–Gastaut syndrome, as well as early infantile epileptic encephalopathies unresponsive to ACTH and ASMs." (PMID 36833226, 2023).
exophthalmos (1 paper, 2020). "Wildmeister and Horster showed that administration of TRH did not induce exophthalmos in goldfish, while treatment with TSH did." (PMID 33329404, 2020).
gastric ulcer (1 paper, 2018). An ulcerated lesion in the mucosal surface of the stomach. "Microinjection of neurotransmitters or neuropeptides including γ-aminobutyric acid, β-endorphin, dopamine, thyrotropin-releasing hormone, and CRH into the CEA results in the attenuation or aggravation of stress-induced gastric ulcers." (PMID 30171524, 2018).
hemochromatosis (1 paper, 2024). A disorder of iron metabolism characterized by a triad of HEMOSIDEROSIS; LIVER CIRRHOSIS; and DIABETES MELLITUS. "A TRH stimulation test with 500 μg was conducted in 4 male hemochromatosis patients and 18 male healthy controls." (PMID 39037546, 2024).
hyperlipemia (1 paper, 2024). "Further KEGG analysis of neurons SAI revealed that TH synthesis was decreased and TH signaling pathway was down-regulated, suggesting that PKCδ-mediated microglial activation may specially cause TRH neurons damage in hyperlipemia brain." (PMID 38250049, 2024). "Meanwhile, we confirmed the decreased TRH levels in hyperlipemia brains." (PMID 38250049, 2024). "Furthermore, TRH level negatively correlated with hyperlipemia severity." (PMID 38250049, 2024).
Hypoxemia (1 paper, 2025). An abnormally low level of blood oxygen. "Hypoxemia: Hypoxemia can cause hypothalamic–pituitary dysfunction, leading to a delayed response of thyroid-stimulating hormone (TSH) to thyrotropin-releasing hormone (TRH), which affects the synthesis and metabolism of peripheral thyroid hormones." (PMID 40385580, 2025).
infantile spasms (1 paper, 2014). A rare epilepsy syndrome characterized by onset of epileptic spasms in infants between 2 and 12 months of age, and rarely up to 24 months. "Thyrotropin-releasing hormone (TRH) also shows promising results in clinical studies for the treatment of infantile spasms." (PMID 24705860, 2014).
inflammatory bowel disease (1 paper, 2020). A spectrum of small and large bowel inflammatory diseases of unknown etiology. "An accumulation of neuropeptides, including TRH, in the lumen of the colon of patients with inflammatory bowel disease is noticeable; animal models of the disease might shed light about TRH-DE role in this pathology, if any." (PMID 32457627, 2020).
ischemia (1 paper, 2023). A hypoperfusion of the BLOOD through an organ or tissue caused by a PATHOLOGIC CONSTRICTION or obstruction of its BLOOD VESSELS, or an absence of BLOOD CIRCULATION. "Particularly susceptible to neuronal loss during those episodes of ischemia are the hippocampal granular cells of the dentate gyrus, which interestingly, exhibit an increased expression of TRH mRNA specifically when starting the reperfusion process after cerebral ischemic injury." (PMID 37446225, 2023).
lung squamous cell carcinoma (1 paper, 2025). "We identified six hormone levels to be significantly associated with lung squamous cell carcinoma (LUSC): total testosterone, oestradiol, thyrotropin-releasing hormone, insulin, parathyroid hormone, and glucocorticoid." (PMID 40017690, 2025).
mastalgia (1 paper, 2023). "The reduction of PRL after VAC administration has been demonstrated elsewhere, including a decrease in TRH-stimulated PRL release and among women with mastalgia." (PMID 38075075, 2023).
migraine (1 paper, 2019). "Using this approach, a total of 6 prohormones were found to correlate with migraine and/or OIH conditions from their respective controls: Vasoactive Intestinal peptide (VIP), PACAP, thyrotropin-releasing hormone prohormone (proTRH), PENK, SCG and proSAAS." (PMID 31649062, 2019).
multiple sclerosis (1 paper, 2013). A progressive autoimmune disorder affecting the central nervous system resulting in demyelination. "Recently was published that oral administration of TRH in mice with experimental autoimmune encephalomyelitis (EAE), an animal model of multiple sclerosis, reduces the spinal cord inflammatory foci without increased frequency of regulatory T cells (Treg) in spleen." (PMID 23964208, 2013).
myasthenia gravis (1 paper, 2024). Myasthenia gravis (MG) is a rare, clinically heterogeneous, autoimmune disorder of the neuromuscular junction characterized by fatigable weakness of voluntary muscles. "It has been proposed that the TSH response to TRH is attenuated in patients with myasthenia gravis, causing an increase in basic TSH reactivity." (PMID 38405140, 2024).
oropharyngeal cancer (1 paper, 2025). Carcinoma, predominantly squamous cell, arising from the epithelial cells of the oropharynx. "Previous studies have shown that hypermethylation of thyrotropin-releasing hormone (TRH) gene was detected in oral and oropharyngeal cancer." (PMID 41465216, 2025).
ovarian serous cystadenocarcinoma (1 paper, 2022). A malignant serous cystic epithelial neoplasm arising from the ovary. "In addition to the high expression level of TRH in AML, only ovarian serous cystadenocarcinoma (OV) had a significantly differential expression of TRH compared with the normal ovaries (p < 0.05)." (PMID 36291567, 2022).
pituitary deficiencies (1 paper, 2015). "In this study, the majority of patients with type 2 responses had isolated TSH deficiency (67%), whilst all patients with type 3 TSH responses to TRH had combined pituitary deficiencies." (PMID 26416826, 2015).
proctitis (1 paper, 2020). An inflammatory process affecting the anus. "The ALG1L2 mapped to the significant CNV region on chr3:129690192–129,896,364 (along with TRH and FAM86HP) was also found to be associated with proctitis in the transcriptomic analysis of whole-blood tissue, while the other two genes (TRH & FAM86HP) were not predicted in either of the two tissues." (PMID 33008348, 2020).
prostatitis (1 paper, 2025). An infectious or non-infectious inflammatory process affecting the prostate gland. "Antibiotic rifaximin (RF) modulates prostatic TRH and TRH-like peptide levels—with the largest peripheral tissue changes in the prostate—via gut microbiome alteration, indicating the gut microbiome-TRH signaling pathway as a potential intervention target for prostatitis." (PMID 40687578, 2025).
resistant hypertension (1 paper, 2020). "This study found TRH on 29 ambulatory hypertensive patients, which made the prevalence of resistant hypertension to be 8.6% [CI:0.056–0.116]." (PMID 32343723, 2020). "On the contrary, this finding’s treatment resistance was quite higher when it is compared to a study done in china which illustrated a TRH prevalence of 1.9% and Israel with resistant hypertension prevalence of 2.2%." (PMID 32343723, 2020).
skin abnormalities (1 paper, 2013). "Indeed, as TRH receptor mutations have not been reported to cause skin abnormalities, it is certainly plausible that TRH may exert its wound healing-promoting effects via TRHR-independent mechanisms." (PMID 24023889, 2013).
Tertiary hypothyroidism (1 paper, 2024). "Tertiary hypothyroidism is caused by hypothalamic dysfunction, which results in decreased levels of thyrotropin-releasing hormone (TRH), causing a decrease in TSH and T3/T4." (PMID 39184762, 2024).
thyroid medullary carcinoma (1 paper, 2020). "A rat thyroid medullary carcinoma cell line, CA77, is known to synthesize TRH." (PMID 33201916, 2020).
thyroid nodule (1 paper, 2021). A small circumscribed mass in the THYROID GLAND that can be of neoplastic growth or non-neoplastic abnormality. "The relative abundances of multiple butyrate producing microbes are reduced in patients with high-grade thyroid nodules and the relative abundances of L-histidine metabolism pathways are associated with thyrotropin-releasing hormone." (PMID 33791245, 2021).
thyroid tumor (1 paper, 2023). A benign or malignant neoplasm affecting the thyroid gland. "Studies have shown that stimulation of thyroid tumor cells with thyrotropin-releasing hormone (TRH) induces Ca2+ oscillations, which in turn activate the mTOR pathway." (PMID 37056339, 2023).